BEND2 (BEN domain containing 2)
Synonyms: CXorf20; MGC33653
Tractability: No criterion of Open Targets' tractability assessment is met for any kind of drug.
Gene: Protein-coding gene on chromosome X (18,162,931 to 18,220,886, reverse strand). Ensembl gene ENSG00000177324.
Subcellular location: Nucleus
Gene Ontology:
Molecular function: protein binding; DNA binding
Cellular component: nucleus
Homologues: Orthologues: chimpanzee BEND2 (97% identical), macaque BEND2 (78% identical), dog BEND2 (40% identical), tropical clawed frog selenon (3% identical), zebrafish selenon (3% identical), zebrafish zgc:113423 (2% identical), rat AABR07037896.1 (2% identical), mouse Bend2 (2% identical). Paralogues in human: SELENON (3% identical), HOATZ (2% identical).
Diseases named in the same sentence as BEND2 in open-access papers:
BEND2 is named in the same sentence as 24 diseases in open-access papers, as found by Europe PMC text mining. Sharing a sentence is not in itself a finding about the gene and the disease. The quoted sentences say what the papers report.
astroblastoma (7 papers, 2018 to 2025). "In decreasing order of frequency, EWSR1, MN1, and MAMLD1 are the reported fusion partners of BEND2 in astroblastoma-like gliomas." (PMID 36690805, 2023). "In the fifth CNS WHO classification, MN1 is part of the diagnosis of a “circumscribed astrocytoma”, Astroblastoma MN1-altered, characterized by fusions of MN1 with BEND2 or CXXC5 genes." (PMID 39409964, 2024). "EWSR1::BEND2 fusions are recurrent in a specific subtype of astroblastoma that is closely related to ‘astroblastoma, MN1-altered′, an entity that harbors MN1 GF with BEND2 as the typical partner, but they are slightly different in their methylation profile." (PMID 38339014, 2024). "This latter group was specifically associated with gene fusions involving MN1 (22q12.3), usually with BEND2 (Xp22.13), but also the alternative partner CXXC5 (5q31.2), and contained 16/23 cases diagnosed as astroblastoma by the originating centres." (PMID 29348602, 2018).
neuroepithelial tumors (3 papers, 2018 to 2024). "The fusion genes containing BEND2 have been reported in neuroepithelial tumors (MN1-BEND2) and spinal cord astroblastoma (EWSR1-BEND2)." (PMID 36686800, 2022).
mesenchymal tumor (2 papers, 2022 to 2024). "Thus, it would be interesting to investigate whether BEND2-rearranged mesenchymal tumors do express CD99 and its functional role." (PMID 38339014, 2024).
Cushing syndrome (1 paper, 2023). Cushing's syndrome (CS) encompasses a group of hormonal disorders caused by prolonged and high exposure levels to glucocorticoids that can be of either endogenous (adrenal cortex production) or exogenous (iatrogenic) origin. "In summary, we herein have reported gene fusions involving BEND2, BCOR and TFG in four successfully tested ACTH-producing and Cushing syndrome-associated NENs of the pancreas, but not in those from non-pancreatic origin." (PMID 36690805, 2023).
female infertility (1 paper, 2025). Diminished or absent ability of a female to achieve conception. "Our data shows that the depletion of BEND2 may lead to premature ovarian insufficiency (POI), which is also a significant cause of female infertility in humans, and its underlying genetic causes are mainly unknown." (PMID 40833257, 2025).
hypospadias (1 paper, 2025). Hypospadias is the displacement of the urethral meatus on the ventrum of the penis. "This is hypothesized to cause a gain-of function effect of BEND2 and resulting in hypospadias in the proband; however, additional functional studies are required for confirmation." (PMID 40597352, 2025).
meningioma (1 paper, 2018). A generally slow growing tumor attached to the dura mater. "Analysis for fusion transcripts in these latter samples showed a consistent apparent inter-chromosomal translocation between MN1 (meningioma disrupted in balanced translocation 1, 22q12.1) and BEND2 (BEN domain containing 2, Xp22.13)." (PMID 29348602, 2018).
pancreatic NET (1 paper, 2023). "In addition, a CDH7::BEND2 fusion has been found in a case report of a hepatic metastasis of a pancreatic NET G3, but there was no mention of ectopic ACTH secretion by the tumor." (PMID 36690805, 2023).
pancreatic neuroendocrine neoplasm (1 paper, 2021). A neoplasm with neuroendocrine differentiation that arises from the pancreas. "Further, in a landmark study of 102 cases of pancreatic neuroendocrine neoplasms subjected to whole-genome sequencing, EWSR1 gene fusions were seen in a small percentage (3%); these included novel fusions such as BEND2 as well as one case of EWSR1 exon 7–FLI1 exon 6 gene fusion." (PMID 34698236, 2021).
tumor (8 papers, 2018 to 2025). "MN1 and BEND2 immunoreactivity were also confirmed by western blot in a MN1-BEND2 case with available frozen tumor (C29)." (PMID 35440587, 2022). "While whether this truncated protein is functional is yet to be determined, multiple reports indicate that BEND2 proteins with truncated N-terminuses have been found in various types of tumours, suggesting that this protein is likely functional." (PMID 40597352, 2025). "The tumor was further evaluated using targeted RNA-seq in order to identify the gene fusion partner, revealing a fusion transcript EWSR1::BEND2 between EWSR1 exon 11 and BEND2 exon 5 (Table A1)." (PMID 38339014, 2024). "No similarity was seen with the recently described HGNET_MN1 tumor type, which is characterized by MN1:BEND2 and MN1:CXXC5 (but not PATZ1) fusions." (PMID 34417833, 2021).
BEND2 also shares sentences with these, for which no sentence is quoted: glioma (2 papers); anaplastic ependymoma (1); astrocytoma (1); CNS tumors (1); ependymal tumor (1); ependymoma (1); Ewing sarcoma (1); Infertility (1); Intellectual disability (1); nervous system tumors (1); Osteoblastoma (1); Premature ovarian insufficiency (1); rhabdomyosarcoma (1); spinal cord ependymoma (1).